STAT3 (signal transducer and activator of transcription 3)
Diseases named in the same sentence as STAT3 in open-access papers (continued):
Sharing a sentence is not in itself a finding about the gene and the disease.
infection (continued). "STAT3 knock-down cells had significantly more apoptosis than control knock-down cells during H5N1/483 infection." (PMID 27344974, 2016). "JAK1, STAT1, and STAT3 expression levels were dramatically elevated in infection groups of both db/db and C57 mice." (PMID 27995146, 2016). "Immunoblotting showed that after PAO1 infection, the levels of both total and phosphorylated STAT3 were increased in Lyn-silenced MH-S cells, indicating that Lyn regulates the IL-6/STAT3 signaling pathway." (PMID 29263906, 2016). "To gain more insight in the STAT3-controlled cytokines, we quantified the release of 30 different cytokines by scramble- and siSTAT3-hMΦ, 24 hours after infection with M. tuberculosis H37Rv." (PMID 27384401, 2016). "One of the most remarkable features of the LN infection by the Sterne strain is the upregulation of transcriptional factors STATs (especially strong for phosphorylated STAT3)." (PMID 26091359, 2015). "Together, our results show that a defect in activating Stat3 in intestinal epithelial cells leads to the development of a strikingly more severe intestinal inflammation after infection with C. rodentium as compared to wildtype mice." (PMID 25799189, 2015). "Although Stat3ΔLep/ΔLep:KrasG12D/+ males showed a median survival of 118 days post AdCre infection, the control Stat3+/+:KrasG12D/+ male littermates survived 175 days." (PMID 25734337, 2015). "For the first time, we directly demonstrate a critical role for Stat3 activation in intestinal epithelial cells upon infection of mice with Citrobacter rodentium – a murine pathogen that mimics human infections with attaching and effacing Escherichia coli." (PMID 25799189, 2015). "Severe acute respiratory syndrome coronavirus (SARS-CoV) infection of Vero E6 cells results in STAT3 dephosphorylation at Tyr705." (PMID 26199948, 2015). "We constantly observed that in AGS cells infected with H. pylori in the presence of IL-6, STAT3 phosphorylation reappeared at 120 min after it declined to almost undetectable levels at 60 min after infection." (PMID 24824519, 2014). "Phospho-STAT-3 protein in primary duck cells was expressed constitutively and remained strongly expressed at 24 h of infection with H5N1-tyEng91 or H5N1-tyTR05 virus." (PMID 25431115, 2014). "In primary chicken cells, by contrast, phospho-STAT-3 was weakly expressed before infection and undetectable at 24 hpi with H5N1-tyEng91 or H5N1-tyTR05 virus." (PMID 25431115, 2014). "After exposure of PC3M-1E8 cells to the lentivirus encoding shRNA of STAT3 and GFP, most of the cells expressed GFP 72 hours after the infection." (PMID 25261365, 2014). "Although cyclin D1 is known to be a target gene of EGFR and STAT3, its transcriptional regulation remains elusive after the infection of virus." (PMID 24499623, 2013). "This analysis also placed STAT3 as a central interaction node among the genes whose expression was stimulated by Salmonella late in infection." (PMID 24098123, 2013). "In fact, infection of macrophages by S. Typhimurium, which results in the activation of Toll like receptors and the production of cytokines, leads to STAT3 activation." (PMID 24098123, 2013). "As expected, Socs3 mRNA levels were reduced in M. tuberculosis-infected Socs3fl/fl LysM cre BMM when compared to controls, and in vitro infection of BMM with M. tuberculosis stimulated STAT3 phosphorylation that was prolonged in Socs3fl/fl LysM cre BMM." (PMID 23853585, 2013). "Infection with Lm increased K63-ubiquitination of STAT3, which was augmented in Cyld−/− as compared to WT mice." (PMID 23825949, 2013). "In HepG2 cells, STAT3 phosphorylation was detected as early as 2 h post-infection, peaked 1 day post-infection, and decreased thereafter." (PMID 23555719, 2013).
infection (continued). "SOCS3-deficient BMM showed increased STAT3 activation and diminished secretion of TNF and IL-12 after infection with either M. tuberculosis or BCG." (PMID 23853585, 2013). "STAT3 phosphorylation was observed throughout infection, with continuously increasing levels until at least 20 h post-infection." (PMID 24098123, 2013). "We treated uninfected cultured epithelial cells with supernatants obtained from S. Typhimurium infected cells at different times after infection and examined STAT3 phosphorylation in the treated cells." (PMID 24098123, 2013). "A complete virus clearance and an attenuated inflammation were examined in both groups WT and STAT3 KO mice 4 weeks after infection, but the cardiac function in STAT3 KO mice was significantly decreased in contrast to the infected WT mice." (PMID 22675647, 2012). "The results demonstrate that STAT3 is activated by P. berghei ANKA (PBA) infection in vivo and Heme in vitro." (PMID 22479586, 2012). "The infected WT and the infected STAT3 KO mice were hemodynamically characterized 28 days after infection and compared to the hemodynamic function of their respective non infected controls." (PMID 22675647, 2012). "Reduction of Stat3 levels through infection with the sh-Stat3 lentivirus vector gave similar results." (PMID 23244248, 2012). "Even more Mac3+ cells were found in cardiac tissue of CVB3-infected STAT3 KO mice compared to CVB3-infected WT mice (WT: 3.72 ± 1.29 fold versus STAT3 KO: 8.86 ± 2.12 fold, P = 0.0232) 28 days after infection." (PMID 22675647, 2012). "Although it is known that the proinflammaotry NF-κB pathway, Src family kinase and Rho kinase modulate host response to P. falciparum, little is known about the role of STAT3 in Plasmodium strain infection." (PMID 22479586, 2012). "The expression of the vascular cell adhesion molecule VCAM was analysed using cryosections of untreated and CVB3-infected WT and STAT3 KO mice 28 days after infection." (PMID 22675647, 2012). "Our results showed that at a MOI between 10–200∶1, H. pylori was able to induce STAT3 transcription and STAT3 pY705 phosphorylation within 6 h of infection." (PMID 22662230, 2012). "Complementary analysis of Il6, Stat3, and Il6ra gene expression by qRT-PCR similarly identified peak upregulation of Stat3 and Il6ra early at day 2 pi, and persistent upregulation of Il6 throughout infection." (PMID 22679491, 2012). "The hemodynamic characterisation clearly shows a significantly reduced cardiac function of CVB3-infected STAT3 KO mice compared to CVB3-infected wild-type mice 28 days after infection." (PMID 22675647, 2012). "In the present study, we determined that STAT3 is activated during PBA infection in vivo and Heme in vitro." (PMID 22479586, 2012). "Our results also indicate that the activation of STAT3 precedes the peak levels of HO-1 induced by PBA infection, which is consistent with previous report." (PMID 22479586, 2012). "Peritoneal exudate cells (PEC) were collected 2, 3 and 4 days post-infection and analyzed by Western blot for STAT3 and STAT6 phosphorylation." (PMID 21931552, 2011). "In the infection model, levels of STAT3 and phosphorylated STAT3 are either moderately increased (in WT mice) or remained unchanged (in plg-/- mice) as compared to uninfected controls." (PMID 21931850, 2011). "Previously, we found that infection with Type I RH tachyzoites inhibited MØ responses to LPS and other TLR ligands, and we linked this inhibition phenotype to STAT3 activation." (PMID 21931552, 2011). "In the absence of ROP16, we also detected rapid accumulation of phosphorylated STAT3 that was greatly reduced by 1.5 hr post-infection even though total STAT3 levels remain elevated." (PMID 21931552, 2011). "In the complemented ΔROP16:1 strain, levels of phosphorylated STAT3 were maintained in a manner similar to infection with parental parasites." (PMID 21931552, 2011).
infection (continued). "Infection of mouse bone marrow-derived MØ induces rapid and sustained activation of STAT3, a transcription factor through which the anti-inflammatory cytokine IL-10 exerts its function." (PMID 21931552, 2011). "Infection with STAT3-shRNA reduced the mRNA levels of ROR1 and the Stat3-regulated genes STAT3, Bcl2, Bcl-XL, Cyclin D1, c-Myc, WAF1/p21, and Pim1." (PMID 20686606, 2010). "In connection with these observations, our data indicate that reduced phosphorylation of STAT3 is a plausible contributor to the pathogenicity of the toxigenic infection." (PMID 19416348, 2009). "After 4 day of infection with a higher dose of rAd/Stat3 (moi = 1000), a cell viability assay (MTT) also revealed that WH and UMUC with higher content of p-Stat3 only maintained 34.8 ± 1.4% and 51.9 ± 8.5% cell viability of untreated controls." (PMID 18939995, 2008). "As a negative regulator of apoptosis, we hypothesized that STAT3 contributes to apoptotic inhibition at late time points during infection." (PMID 41115066, 2025). "While STAT3's role in Theileria infections is well-established, the functions of the others (GTF2F1 and NFATC1) remain unclear." (PMID 40368139, 2025). "Phosphorylation of STAT3 was significantly increased following RVFV infection, but little to no phosphorylation was observed in cells infected with the RVFV ΔNSs variant, demonstrating the crucial role of NSs for the increase in STAT3 phosphorylation during infection." (PMID 41157666, 2025). "Our results show that the psarAI168R mutant strain has significantly slower and lower overall amounts of STAT3 phosphorylation during infection compared to the wild-type complemented strain; this phenocopies the pattern of phosphorylation during infection with the psarA:gp130-expressing strain." (PMID 40188438, 2025). "To determine whether STAT3 meaningfully contributes to bacterial replication or survival in host cells, we assessed infection using RT-qPCR following pretreatment with DMSO or C188-9." (PMID 41115066, 2025). "Thus, to evaluate STAT3 involvement throughout infection, we measured both STAT3 phosphorylation at Y705 and nuclear translocation by western blot and immunofluorescent microscopy, respectively." (PMID 41115066, 2025). "It has been reported that, during the early stage of T. gondii type I and III infection, mouse macrophages tend to M2 phenotype through the STAT3/STAT6 pathways by rhoptry protein 16, while type II infected macrophages tend to M1 phenotype via dense granule protein 15 phosphorylated NF-κB." (PMID 40394721, 2025). "Additionally, RSV has been found to impair the activation of the STAT3 pathway in memory T cells, reducing their ability to clear the infection effectively." (PMID 40407543, 2025). "In addition, multiple immunohistochemical and flow cytometric assays revealed that the inhibition of p-Stat3 limited Th17 cell development during PmA infection." (PMID 41402924, 2025). "Recently, however, the activation of the Hedgehog and NOTCH signaling pathways following viruses’ infection (including SARS-CoV-2) has been reported to induce STAT3 upregulation, to increase IL-6 expression, and lead to the observed detrimental outcomes, such as fibrosis." (PMID 40156072, 2025). "Additionally, IL-6 can interact with GP130 on the cell membrane, inducing STAT3 phosphorylation and contributing to the onset and progression of infections." (PMID 41137299, 2025). "Furthermore, both pharmacological inhibition and genetic knockout of STAT3 significantly reduced bacterial load, highlighting its critical role in supporting infection." (PMID 41115066, 2025). "Moreover, high-dose pH1N1 infection induces an excessive early immune response, characterized by massive neutrophil recruitment, cytokines storm, and STAT3 activation." (PMID 41488475, 2025).
infection (continued). "Interestingly, TRP75 is the only TRP known to interact with signal transducer and activator of transcription 3 (STAT3), an immunomodulatory transcription factor with well-established roles in both malignancy and infection (6, 12, –, 15)." (PMID 41115066, 2025). "Therefore, we further investigated STAT3 activation dynamics and effects of its inhibition on infection." (PMID 41115066, 2025). "Furthermore, considering the impact of STAT3 abrogation on infection, the outcome of these experiments suggests that STAT3 has other pro-infection functions unrelated to inhibiting apoptosis." (PMID 41115066, 2025). "Antibody-dependent enhancement (ADE) of infection, which would be expected to engage the FcΥR and potentially activate Vav/Rac/Rho signaling, results in upregulation of STAT3 and IL-6 during ZIKV and DENV infection and additionally downregulates ISGs, as reviewed." (PMID 38054722, 2024). "Furthermore, we also confirmed that H pylori promoted DAB2 expression and activation of STAT3 signaling after infection of mice with H pylori PMSS1." (PMID 38481347, 2024). "Therefore, RSV utilizes virus-specific regulation of STAT3 signaling and apoptotic cell death to induce severe infection in neonatal bronchial epithelium." (PMID 39484716, 2024). "Therefore, inhibitors such as cucurbitacin I and Stattic can be utilized as antimicrobial agents, and the JAK2/STAT3 pathway can be a therapeutic target of infection with intracellular bacteria as well." (PMID 39255287, 2024). "In innate immunity, STAT3 regulates critical steps during emergency granulopoiesis to help contain infection, restrains neutrophil production to limit inflammatory responses, and suppresses the maturation and activation of dendritic cells to induce immunosuppressive effects." (PMID 38611065, 2024). "Infection with PCV2 resulted in enhanced STAT3 phosphorylation (p < 0.001)." (PMID 39588099, 2024). "In summary, our study identifies impaired antiapoptotic STAT3 activation in ciliated cells following RSV infection as an age-related mechanism underlying severe RSV disease in infants, which can be targeted to reduce infection and inflammation." (PMID 39484716, 2024). "Thus, the JAK2/STAT3 pathway is important for the infection and pathogenesis of various bacterial intracellular infections." (PMID 39255287, 2024). "Finally, the ratio between pro-MMP9/TIMP1 protein levels in the supernatant of S. aureus–stimulated samples was elevated in STAT3-deficient compared with WT BMDM, in particular at 48 h after infection." (PMID 37982695, 2024). "The hyperinflammatory phenotype observed in our infection model during STAT3 deficiency did not affect pathogen uptake, intracellular survival, or overall pathogen clearance in vitro or in vivo." (PMID 37982695, 2024). "Cytokines, growth factors, and hormones function in JAK/STAT3/5 signaling pathway, and they could regulate the intestinal response to infection, inflammation, and tumorigenesis." (PMID 39136000, 2024). "Indeed, GSEAs showed a downregulation of gene sets such as TNF-alpha signalling via NF-κB, IL-6/JAK/STAT3 signalling and inflammatory response after infection with the low-virulence isolate at an early stage of infection." (PMID 37520552, 2023). "However, treatment with AG490, a selective inhibitor of JAK2, only marginally reduced STAT3 phosphorylation levels upon M81 infection." (PMID 37830871, 2023). "Further in-depth studies to dissect the precise role of STAT3 in mediating viral early infections could provide more valuable insights into viral pathogenesis." (PMID 37099596, 2023). "Here, we reported that IL-22 expression was highly facilitated after DHAV-1 infection both in vitro and in vivo, and the increase in expression might be due to duck STAT3 directly antagonizing STAT1 and leading to an increase in IL-22 promoter activities." (PMID 37391858, 2023).
infection (continued). "With respect to HHV-8, STAT3 is activated by de novo infection of endothelial cells and in latently infected endothelial and PEL cells and plays critical roles in sustaining the viability of latently infected cells and enabling efficient productive replication." (PMID 37983265, 2023). "We also noted that infection with LDPm or LDAm induced STAT3 phosphorylation in BMDCs." (PMID 37202419, 2023). "Based on this, we hypothesize that IAV infection stimulates the expression of miR-141 in infected cells to regulate the expression profile of MxA as an interferon-inducible gene and STAT3, which is stimulated upon infection in response to IL-6 production." (PMID 37596622, 2023). "Given that DMI suppresses IL-6 and IL-10 and induces autophagy in macrophages during infection, we evaluated its effect on the activation of the transcription factor STAT3, which modulates gene expression in response to IL-6 and IL-10 and the suppression of autophagy." (PMID 36882813, 2023). "Our results showed that TBEV potently inhibited the STAT3 phosphorylation in A549 cells, which may account for the viral survival and propagation and thereby establish infection." (PMID 37378295, 2023). "However, infection with the EBNA2 deletion mutant or with VLPs was less efficient at inducing p-STAT3 than infection with M81 wt or with M81/∆gp110." (PMID 37830871, 2023). "Indeed, astrocytes showed significant increases in JAK2, STAT3, and phosphorylated counterparts after gp120 infection." (PMID 36997969, 2023). "Finally, we evaluated the impact of p38 and STAT3 inhibition on the expression of latent gene transcripts at 6 hours post-infection." (PMID 37830871, 2023). "Moreover, DMI significantly downregulated the activation of signal transducer and activator of transcription 3 signaling during infection with Mtb, BCG, and Mav." (PMID 36882813, 2023). "However, 1,25(OH)2D3 treatment not only inhibited p-STAT1 and p-STAT3 levels at 1 h post-infection, but also at 24 h post-infection in IPEC-J2 cells." (PMID 36142545, 2022). "The mRNA expression of porcine STAT3 was altered significantly in IPEC-J2 after infection by PEDV or in the jejunum of piglets during weaning, but its expression in the gastrointestinal tract of sucking piglets was unknown." (PMID 36406089, 2022). "When GSEA analyses were conducted to identify cell line–specific changes, by excluding commonly altered pathways, we observed that the majorly altered gene sets in U37360 Gy cells belonged to “interferon response genes”, “STAT3 targets”, and infection-related pathways." (PMID 35806055, 2022). "B. henselae wild-type triggered STAT3 phosphorylation 1 h post-infection (hpi)." (PMID 35910598, 2022). "Knockdown of STAT3 attenuated the suppressed IFN-mediated antiviral response to EV71 infection and led to a reduction in viral replication, demonstrating the role of STAT3 in maintaining the balance of inflammatory response in astrocytes and antiviral response in the CNS during infection." (PMID 36325336, 2022). "In contrast, by flow cytometry and immunofluorescence analyses of fresh “untouched” crypt samples for stem cells and TA cells, we found that loss of Il-22, epithelial Stat3, or Il-18 in mice indeed cause a reduction of Lgr5+ and Ki67+ crypts at the steady state and during AIEC infection." (PMID 35169117, 2022). "Importantly, we found that Stat3 signaling was the activated in both mouse and rat lungs throughout the infection phase." (PMID 35617354, 2022). "Besides, we found that in GES-1 and AGS cell lines, the expression level of p-STAT3 during the high-Trx1 HP infection was much higher than the low-Trx1 HP group." (PMID 35958524, 2022). "In contrast to senescent cells, STAT3 seems to be a positive regulator of iNOS in non-senescent cells, possibly explaining why its inhibition caused an increase in infection." (PMID 34746026, 2021). "Metacestode infection elicited high levels of IL-10 and upregulated STAT-3 in peritoneal cells." (PMID 33461599, 2021).